INS (insulin)
Diseases named in the same sentence as INS in open-access papers (continued):
Sharing a sentence is not in itself a finding about the gene and the disease.
diabetes (continued). "Diabetes mellitus (DM) is a chronic disorder related to glucose metabolism and the secretion of insulin, with serious clinical complications resulting from the damage of macrovascular and microvascular blood vessels." (PMID 35744822, 2022). "The use of technologies like sensor augmented insulin pumps and hybrid closed loop systems is increasing in children and adolescents with diabetes." (PMID 35712259, 2022). "Individuals with diabetes receiving insulin therapy were matched with subjects receiving oral antidiabetic agents for age and gender." (PMID 35705192, 2022). "Nevertheless, traditional BG monitoring will continue to be the way that most people who take insulin to treat diabetes monitor their diabetes for some time to come." (PMID 34921531, 2022). "Previous studies have reported that probiotics exhibit beneficial effects on insulin antagonism in animal models of diabetes." (PMID 35885395, 2022). "These genes also mapped to several relevant KEGG pathways, including type 1 diabetes mellitus, insulin secretion, PI3K-Akt signaling and diabetic cardiomyopathy." (PMID 35456489, 2022). "The N-oleoyl glycine can potentially increase insulin sensitivity and suppress obesity and diabetes." (PMID 36032143, 2022). "Because only 7.0% (10 / 143) of the women with diabetes were treated with insulin, this factor was excluded from further analysis." (PMID 36451171, 2022). "Diabetes mellitus is a metabolic defect disease with hyperglycemia as the main symptom, mainly due to decreased insulin secretion and insulin resistance." (PMID 36187097, 2022). "Out of the four AIM subgroups, hypometabolic obesity (LMO) group was characterized by decompensated insulin secretion and high incidence of diabetes (99.2%) pre-surgery." (PMID 36407309, 2022). "Diabetes is characterized by hyperglycemia due to impaired insulin secretion and/or resistance to the peripheral action of insulin, in insulin-sensitive tissues, or both." (PMID 35208257, 2022). "The group with elevated HbA1c also had a higher prevalence of smokers, hypertension and diabetes, in addition to a higher insulin use." (PMID 36235713, 2022). "Even after the discovery of insulin, infection has remained an important issue, though macrovascular and microvascular diseases are the main complications of diabetes." (PMID 35629125, 2022). "Restoration of first-phase insulin release to intravenous glucose administration (1–4 weeks after Roux-en-Y gastric bypass or biliopancreatic diversion) has been consistently observed, may occur before any significant weight loss and contributes to diabetes improvement or remission." (PMID 35806437, 2022). "Pre-LTx diabetes was present in 30.8% (n = 4) of patients; 23.1% (n = 3) had peripheral neuropathy, and 1 patient was insulin-dependent." (PMID 35282328, 2022). "At a 30 min PH, lower minimal glucose and HbA1c, higher LBGI, DVL, daily and basal insulin doses, diabetes duration, proteinuria, eGFR, and BMI demonstrated the highest importance." (PMID 36013211, 2022). "Using insulin for treating diabetes (p < 0.01), and health status (p < 0.01) were significantly associated with being delayed in getting prescription medications." (PMID 35893717, 2022). "Type 1 diabetes mellitus (T1D) is a metabolic disorder characterized by chronic hyperglycemia resulting from defects in insulin secretion, action, or both, which leads to abnormalities of carbohydrate, fat, and protein metabolism." (PMID 36231246, 2022). "Previous studies have shown cold acclimation increases BAT mass and BAT thermogenesis by modulating and improving insulin sensitivity in healthy humans (1 month acclimation at 19°C) or patients with type 2 diabetes mellitus (10 days at 14–15°C)." (PMID 36017333, 2022). "The increasing IL-6, IL-1α, TNF-α and TGF-β expression in the lungs of diabetic rats indicates that the expression of proinflammatory cytokines was upregulated in diabetes and was downregulated by insulin and Rb1 treatment." (PMID 36367996, 2022).
diabetes (continued). "In this population-based cross-sectional study of NHANES data over the past 3 decades, glycemic control stagnated and racial and ethnic disparities increased among US adults with diabetes who received insulin." (PMID 36538330, 2022). "Downregulation of SLC2A2 is associated with not only T2D but also neonatal diabetes and early childhood diabetes, suggesting a likely role in insulin secretion." (PMID 35788821, 2022). "Other nutrients, hormones and neurotransmitters activate insulin secretion, but in terms of diabetes, glucose is the most important chemical factor." (PMID 36128718, 2022). "After more than three decades of investigation, in 2000, the Edmonton group reported their remarkable work that 100% of patients (n=7) with labile diabetes who received islet transplantation and corticosteroid-free immunosuppression become insulin independent." (PMID 35903090, 2022). "Diabetes mellitus is a serious chronic disease characterized by high sugar levels in the blood that result from dysregulated insulin production, insulin utility, and its signaling pathway." (PMID 35672565, 2022). "The major pathophysiological event contributing to the development of type 2 diabetes mellitus is thetarget tissues to insulin action." (PMID 37693081, 2022). "The collection of amyloid proteins was thought to be due to elevated insulin and amylin in the fetus - in response to diabetes in the mother and increased glucose in the fetus." (PMID 36712777, 2022). "It was determined that C albicans has direct and indirect effects on insulin secretion and should be seriously taken into account as one of the possible factors involved in the pathogenesis of diabetes." (PMID 36397429, 2022). "If the insulin prefilled pens would dominate the market, just as expensive analog insulin is replacing the cheaper human insulin, the affordability of diabetes treatment would be gravely compromised." (PMID 35431962, 2022). "Registry recently reported that patients with concomitant chronic heart failure (CHF) and impairment of insulin axis (either insulin resistance—IR or diabetes mellitus—T2D) display increased morbidity and mortality." (PMID 35710369, 2022). "Correlations between Age, FBS, HBA1c TC, TG, HDL-C, LDL-C and insulin and study variables (Age, BMI, and duration of diabetes)." (PMID 39450303, 2022). "We have provided evidence that islet cells are deprived of Glrx5, correlating with impaired insulin secretion during diabetes in genetically obese mice." (PMID 35453472, 2022). "Antibody-trapping of the oxidized form of PTP1B, a highly touted drug target for diabetes and obesity, has been shown to increase insulin signaling in vitro." (PMID 35587260, 2022). "We were able to determine indicators of inpatient glycemic management (ie, HbA1c checked, insulin started, or diabetes service consulted) and identified that individuals with one or more of these indicators were significantly more likely to be linked to care." (PMID 35333182, 2022). "In fact, inertia in intensifying diabetes therapy and especially in initiating basal insulin in patients with poor metabolic control is a well-recognized problem." (PMID 35864262, 2022). "Polyphenol compounds found in many plants can enhance insulin sensitivity and reduce blood glucose in animal models of diabetes." (PMID 35502441, 2022). "The insulin-induced transcriptomic changes did not overlap with those observed in diabetic placentas highlighting that insulin alone has different effects on diabetes, suggesting differential effects of insulin in healthy and GDM pregnancies." (PMID 35258482, 2022). "Compared to fenofibrate, saroglitazar treatment showed significant reduction in fasting insulin and C-peptide in participants with diabetes, indicating improvement in insulin resistance." (PMID 35605678, 2022).
diabetes (continued). "The antihyperglycemic medication metformin, which increases insulin sensitivity and reduces hyperglycemia and insulin levels, is commonly used in patients with diabetes, and is safe and widely accepted for use in prediabetes." (PMID 35406370, 2022). "Apelin synthesis in adipocytes is stimulated by insulin and its plasma levels are demonstrated to increase in relation to diabetes mellitus, IR, and hyperinsulinemia." (PMID 35913970, 2022). "Type 2 Diabetes Mellitus (DM2), with its onset in early adulthood, is characterized by a progressive loss of β-cell insulin secretion frequently on the background of insulin resistance." (PMID 35204864, 2022). "Recent advances in diabetes technology have led to the development of automated insulin delivery (AID) systems, also known as hybrid closed-loop, closed-loop, or artificial pancreas systems." (PMID 35834298, 2022). "Diabetes is a chronic metabolic disorder characterised by an increased blood glucose level brought on by insufficient insulin production." (PMID 36238678, 2022). "In general, those on insulin had longer duration of diabetes, higher A1C, higher BMI and lower use of metformin and sulfonylureas." (PMID 35189851, 2022). "Generally, diabetes treatment focuses on lowering blood glucose levels, improving insulin sensitivity, and preserving pancreatic β-cells." (PMID 35832521, 2022). "The prognostic literature on diabetes-related hypoglycemia—a potentially lethal and costly side effect of insulin and/or secretagogues—has been dominated by analyses of pre-existing trial or administrative databases." (PMID 35025756, 2022). "Search items included “COVID-19”, “post-COVID”, “long COVID”, “SARS-CoV-2”, “diabetes”, “hyperglycaemia”, “hyperglycemia”, “insulin”, and “depression”." (PMID 35253006, 2022). "The Diabetes Prevention Trial (DPT-1) tested both insulin injections and oral insulin as possible prevention strategies in children at risk for type 1 diabetes; neither intervention was effective." (PMID 35012530, 2022). "On the one hand, anti-diabetes therapy using insulin lowers blood glucose levels but leads to weight gain." (PMID 36145160, 2022). "Regarding the over-represented acyl-carnitine in diabetic patients, hydroxy-butyryl-carnitine, it should be that some acyl-carnitines provide benefits in diabetes, from improving insulin sensitivity to controlling oxidative stress (see Ref." (PMID 36361545, 2022). "Diabetes mellitus is a common disease affecting older adults, coined as a metabolic disorder characterized by ineffective insulin secretion, defective insulin action, or both." (PMID 35736019, 2022). "Environmental, lifestyle and genetic factors contribute to diabetes mellitus, a metabolic disease affecting insulin production and usage that can be further categorized by the molecular characterization of disease onset." (PMID 36128718, 2022). "Currently, treatment of diabetes mellitus includes the use of insulin and various other antidiabetic agents, such as biguanides, β-glucosidase inhibitors, or sulphonylurea." (PMID 36297315, 2022). "Diabetes autoantibodies (glutamate decarboxylase, insulin antibodies, and pancreatic islet cell antibodies) were negative." (PMID 36626423, 2022). "Diabetes is an endocrine metabolic disorder characterized by elevated blood glucose due to impaired insulin secretion or utilization." (PMID 35456051, 2022). "Type 1 diabetes is also known as insulin-dependent diabetes mellitus, which occurs primarily in children and adolescents and requires insulin to restore the blood glucose level." (PMID 35761839, 2022). "T2DM patients with severe CAD were older and had higher proportion of hypertension, longer duration of diabetes, higher body mass index (BMI), higher fasting insulin (FINS), and fasting C peptide (FCP)." (PMID 36238131, 2022).
diabetes (continued). "Brugmansia aurea at 400 mg/kg produced approximately similar results in managing insulin resistance during diabetes as other standard drugs, thus improving insulin action at the cellular level." (PMID 36304231, 2022). "Recruitment will be from diabetes clinics at Hamad Medical corporation, pharmacy lists (insulin treatment), and diabetes registries." (PMID 35710428, 2022). "The past thirty years have seen unrest in diabetes treatment optimization, especially in basic insulin treatment for glycemic control." (PMID 35203540, 2022). "Type 2 diabetes mellitus (T2DM) is an abnormality in glucose metabolism and related metabolic disorders caused by inadequate insulin secretion or ineffective cellular response to insulin." (PMID 36002855, 2022). "Arg is a key substrate for various pathways including vascular Arg-NO-signalling and it also affects insulin signalling in diabetes." (PMID 34991562, 2022). "Type 2 diabetes mellitus (T2DM) is a metabolic disorder of lipids, carbohydrates, and proteins caused by defective insulin action and insulin secretion." (PMID 35406873, 2022). "The fuzzy logic system for insulin calculation considers four inputs: the person’s health, diabetes level, weight, and carbohydrate intake." (PMID 36611472, 2022). "Diabetes mellitus (DM) is an endocrine disorder either due to impaired insulin release, insufficient action or both, resulting in persistent hyperglycaemia." (PMID 36678691, 2022). "Type 2 diabetes mellitus (T2D) is a metabolic disorder that affects approximately 10% of the world population and is characterized by insulin resistance and progressive pancreatic β-cell dysfunction leading to insulin deficiency." (PMID 35742925, 2022). "Treatment with glucose lowering pharmacotherapy has an inherent risk for iatrogenic hypoglycemia, especially in older T2DM patients with a long diabetes duration treated with insulin or sulfonylurea." (PMID 35337110, 2022). "Diabetes is a complex metabolic disease characterized by chronic hyperglycemia due to inadequate insulin secretion or insulin resistance." (PMID 36484062, 2022). "SCFAs overactivate glycolysis and glyconeogenesis pathways and suppress the insulin response in peripheral tissues, leading to diabetes." (PMID 35285096, 2022). "Diabetes is one of the most common diseases and represents a complex and heterogeneous group of chronic metabolic diseases characterized by insufficient insulin secretion and/or an inefficiency of targeted tissues in terms of its metabolic action." (PMID 35330341, 2022). "Diabetes management through hypoglycemic agents, insulin, and diet therapy are very well investigated." (PMID 35334901, 2022). "No notable difference was found between the two groups in general data, fasting insulin level, HbA1c, diabetes duration, and the frequency of coexisting diseases (P < 0.05)." (PMID 35392498, 2022). "OA has previously been reported to attenuate the symptoms of diabetes via increasing insulin secretion and decreasing the deleterious products that facilitate IR." (PMID 35265127, 2022). "Among treated diabetes patients, the rates of oral antidiabetic medications, insulin injection, diet control, and blood glucose monitoring were 78.24%, 34.71%, 85.77%, and 78.24%, respectively." (PMID 35457673, 2022). "Anabolic effects of insulin and insulin-like growth factors can also possibly contribute to diabetes-induced bone deformities." (PMID 36354542, 2022). "The inflammatory periapical response is enhanced in diabetics, leading to a rise in blood glucose with intensification of diabetes, requiring an increase in insulin dosage or therapeutic adjustment." (PMID 35888650, 2022). "The preferred method to manage blood glucose in patients with diabetes receiving PN is to administer a rapid-acting insulin IV." (PMID 36992742, 2022).
diabetes (continued). "GLP-1 is a target for treatment of diabetes because of the primary peripheral functions of inducing insulin secretion from pancreatic β cells, gut emptying and inhibiting glucagon secretion which results in lower blood glucose levels." (PMID 36465634, 2022). "Diabetes is characterized by an increased rate of serum glucose due to defects in insulin secretion, insulin action or both conditions." (PMID 36135647, 2022). "There are few studies upon the process of falling ill, as well as few studies on the process of living with insulin treated diabetes from the diagnosis, present time, and future perspectives." (PMID 35726172, 2022). "Statin users who have developed diabetes had both reduction in insulin secretion and increase in insulin resistance." (PMID 35892446, 2022). "The most common dermatological complication of insulin therapy for glycemic control in diabetes is lipohypertrophy, which has a prevalence ranging from approximately 25% to 65% in the literature." (PMID 35404833, 2022). "Data from 18 distinct studies about 41 exposure–outcome associations were synthesized (by outcome: obesity [n = 18]; blood pressure [n = 9]; glucose, insulin or diabetes [n = 4]; lipids [n = 5]; and MetS [n = 5])." (PMID 35954531, 2022). "Both the nutritional and the insulin regimen need to be considered when controlling blood glucose in patients with diabetes receiving PN." (PMID 36992742, 2022). "Sodium-glucose co-transporter 2 (SGLT2) inhibitors block glucose reabsorption in the renal proximal tubule, an insulin-independent mechanism that plays a critical role in glycemic regulation in diabetes." (PMID 35409011, 2022). "Scientists and investigators had to face many challenges during the development of insulin therapy, and it took more than 100 years since the 19th century to improve insulin therapy against diabetes." (PMID 35723344, 2022). "These metabolites were enriched in obesity-related terms such as “Amino sugar and nucleotide sugar metabolism”, “Amino Sugar Metabolism”, “Insulin signaling pathway” and “Type 2 diabetes mellitus”." (PMID 35568907, 2022). "Factors such as obesity, sedentary lifestyle, and genetic predisposition play a critical role in the development of this type of diabetes, which results from insulin resistance in peripheral tissues, and insulin secretory defects." (PMID 36235503, 2022). "Normally, on the cellular level, dysfunction of the islet β-cells leads to a reduction in insulin production, leading to diabetes." (PMID 36003336, 2022). "Diabetes is a metabolic disorder characterized by hyperglycemia that results from defective insulin secretion, insulin action, or both." (PMID 35356240, 2022). "Insulin resistance, a reduced response of cells to the action of insulin, is a major finding in metabolic disorders such as diabetes mellitus type 2 (T2DM)." (PMID 35242882, 2022). "TGF-b/Smad3 signaling is a pivotal regulator of insulin expression that can be deregulated in diabetes." (PMID 35366956, 2022). "Type 2 diabetes mellitus (T2DM) is a chronic disease characterized by high blood glucose levels and is often associated with insufficient insulin production and/or insulin resistance." (PMID 35139776, 2022). "The discovery and administration of insulin are milestones in the treatment of diabetes, which transforms diabetes from a life-threatening disease to a controllable disease." (PMID 36157449, 2022). "Diabetes mellitus (DM) is a group of metabolic diseases characterized by hyperglycemia, insulin resistance, and impaired insulin secretion." (PMID 35370972, 2022). "This review aimed to identify barriers and facilitators to managing diabetes with insulin in adults with intellectual disabilities." (PMID 35983585, 2022). "More than 100 years after the discovery of insulin, much remains to be done to ensure access to quality diabetes care to prevent complications and minimise disability." (PMID 35850129, 2022).